HK2 (hexokinase 2)
Diseases named in the same sentence as HK2 in open-access papers (continued):
Sharing a sentence is not in itself a finding about the gene and the disease.
tumor (continued). "The glycolytic enzyme hexokinase 2 (HK2) overexpressed in tumor cells ensures the high efficiency of glycolysis in tumor cells and at the same time inhibits the glucose uptake of T cells." (PMID 33614478, 2020). "Hexokinase catalyses the first step in glycolysis of which the HK2 isoform is upregulated by many tumours and is needed to maintain the high glycolytic rate." (PMID 33092283, 2020). "Taken together, these findings demonstrated that HK2 is required for tumor glycolysis and lung squamous cell tumorigenesis." (PMID 32083006, 2020). "MYC is a master regulator of tumor energy metabolism via regulation of enzymes and transporters such as hexokinase (HK2) and glucose transporters (GLUT)." (PMID 32690037, 2020). "We found that HK2 knockdown revised tumor growth and the LA/PA content promoted by circCDKN2B-AS1 overexpression." (PMID 33308298, 2020). "To understand the role of METTL3 in ESCA, we compared METTL3, GLUT1 and HK2 expression between tumor and matched normal tissue specimens from the 57 patients." (PMID 32626532, 2020). "The up‐regulation of HK2 has been reported in several types of human neoplasms, including BC, and the increased protein expression of HK2 was shown to be required for glucose metabolism and cancer cell progression." (PMID 32885590, 2020). "Since changes in glucose metabolism generally confer cancer cells resistance to chemotherapy, inhibition of glycolysis by targeting HK2 can significantly enhance the sensitivity of tumour cells to chemotherapy." (PMID 31994339, 2020). "To address this issue, we evaluated the effects of HK2 overexpression in tumor cells on the clinical response to PD-1 blockades." (PMID 31718692, 2019). "The PVT1/miR-497/HK2 axis which regulates tumor cell energy metabolism is another important pathway that promotes tumor cell proliferation." (PMID 31380270, 2019). "The glycolytic signature and HK2 expression were highest in NSCLCs of so-called tumor microenvironment immune type (TMIT) III, which express high levels of PD-L1 but low levels of CD8, thus being considered poor responders to anti-PD-1/PD-L1 immunotherapy." (PMID 31718692, 2019). "We demonstrated that the natural compound, xanthohumol, has a profound anti-tumor effect on CRC via down-regulation of HK2 and glycolysis." (PMID 31595166, 2019). "As previously demonstrated, PD-L1 upregulates tumoral glycolysis/HK2 expression and therefore, we tried to find the outcomes of upregulated tumoral HK2 expression in anti-tumor immunity." (PMID 31718692, 2019). "Knockdown of HK2 by siRNA in spheroids formed from ascites-derived tumor cells inhibited lactate production, cell migration, invasion, sphere-formation abilities, FAK/ERK1/2 activation, and metastasis- and CSC-related gene expression." (PMID 31212816, 2019). "As expected, HK2 was highly expressed in tumor samples compared to normal samples (67.2% versus 44.8%, P = 0.001)." (PMID 31655629, 2019). "It would have been informative to demonstrate the enhanced Akt-driven glycolysis as the basis of the higher potency in vivo, e.g., in a murine tumor model, by genetic manipulation of key glycolytic enzymes (e.g., HK2) specifically in CD137L-DCs." (PMID 31068941, 2019). "HK2 is highly expressed in tumor cells and is the first to use of mitochondria-synthesized HK2 catalyzes the rate-limiting and first step of glucose metabolism." (PMID 31569385, 2019). "Similar to the in vitro results, the tumor size and HK2 expressions were reduced in GLUT3 knockdown cells (p < 0.01)." (PMID 31817208, 2019). "Western blot demonstrated that HK2 expression was also decreased in the shHK2 group xenograft tumor and GEM treatment also increased HK2 dimer in vivo." (PMID 31426130, 2019). "Hexokinase 2 maintains the high rate of glucose catabolism that is required for the survival of tumour cells, allowing them to sustain a higher rate of proliferation and resistance to cell death signals." (PMID 30818878, 2019).
tumor (continued). "The result showed that knockout of HK2 significantly inhibited tumor growth in HCT116 and HT29 xenograft mouse models." (PMID 31595166, 2019). "CAFs secrete IL-6 in the tumor microenvironment, which contributes to an up-regulation of HK2 via the IL-6R." (PMID 31212816, 2019). "In this study, HK2 expression level was found to be decreased under condition of PLK3 overexpression, while silencing PLK3 increased HK2 expression in tumor cells." (PMID 31655629, 2019). "Several studies demonstrate that hexokinase, particularly its second isoform (HK2), plays a critical role in initiating and maintaining the high glucose catabolic rates of rapidly growing tumours." (PMID 31053173, 2019). "Up-regulation of HK2 was also detected in ovarian ascitic fluid samples compared to primary tumor cells and HOSE cells." (PMID 31212816, 2019). "In light of HK2’s restricted expression in cancer cells and essential role in tumor development, targeting HK2 is considered an attractive therapeutic strategy." (PMID 31201299, 2019). "The xenograft tumor with HK2 knockdown was more sensitive to GEM treatment, and the growth and weight of shHK2 with GEM treatment tumor were decreased more significantly compared with GEM group." (PMID 31426130, 2019). "HK2 gene was significantly and positively correlated with tumor size, whereas PFKFB3 was significantly and positively correlated with COL1A1, COL3A1, and HAS2 genes in TN." (PMID 31428701, 2019). "In this context, degradation of HK2 through CMA activation appears as a pertinent strategy to inhibit tumor formation." (PMID 31623164, 2019). "HK2 is also highly upregulated in tumor cells and HK2 inhibition synergies with anti-tumor treatment and improves response to therapy." (PMID 31428089, 2019). "In contrast, HK2 depletion inhibits the tumor progression in mouse models, providing attractive prospects for tumor therapeutic strategies." (PMID 31607919, 2019). "PVT1 also modulates HK2 expression by competitively binding to endogenous miR-143 in tumor cells, which promotes cell proliferation and metastasis by regulating aerobic glucose metabolism." (PMID 31380270, 2019). "In each of the treatment groups, individual HK1−HK2+ Hep3B/shHK2DOX mice were switched to the DOX-containing diet when their tumor reached 200 mm3 (day 0) to induce HK2 knockdown." (PMID 29988332, 2018). "The expression levels of SIRT3 were lower in the cancer patient tissues but higher in normal tissues, while the expression levels of STAT3, HIF‐1α, GLUT1, LDHA, and HK2 were higher in tumor tissues but lower in normal tissues." (PMID 30094960, 2018). "Sorafenib alone and HK2 depletion alone significantly (p ≤ 0.05, by Student’s t-test) inhibited tumor growth." (PMID 29386513, 2018). "Taken together, this study demonstrates that knockdown of the glycolytic enzyme HK1 but not HK2 results in the deregulation of energetic metabolism via increased HK2 expression and accelerates tumor malignancy through inducing an EMT phenotype." (PMID 29721175, 2018). "In mouse subcutaneous Hep3B/shHK2DOX tumor xenografts, HK2 knockdown by a 4-day DOX treatment in the diet reduced tumor glucose consumption as determined non-invasively by 18F-fluorodeoxyglucose (FDG)/positron emission tomography (PET) imaging." (PMID 29988332, 2018). "HCC tumors express high levels of the HK2 isoform, and its expression is correlated with the pathological stage of the tumor." (PMID 30524660, 2018). "Numerous reports have indicated that HK2 is overexpressed in various cancers and is at least in part responsible for the increased glycolytic flux in tumor cells." (PMID 29696133, 2018).
tumor (continued). "In a mouse xenograft model of HK1−HK2+ Hep3B/shHK2DOX tumor progression, DOX-induced HK2 knockdown initiated when the tumors reached 200 mm3 significantly reduced tumor growth." (PMID 29988332, 2018). "In contrast, HUH7 cells showed a higher expression of 98 metabolic targets upregulated in tumours (e.g. HK2, PKM, PSPH, GLUL, ASNS, and fatty acid synthesis enzymes ACLY, FASN)." (PMID 30176945, 2018). "Despite a rapid growth in tumor size after a week, knockdown of HK2 levels was efficient in suppressing tumor growth compared to the control group." (PMID 29335581, 2018). "We found that HK2 ablation inhibits hepatocarcinogenesis, proliferation and survival and in vivo tumor growth of HCC cells." (PMID 29386513, 2018). "In tumor cells, HK2 is predominantly localized on the OMM, where its translocation is facilitated by an increase in the cellular glucose concentration." (PMID 29298880, 2018). "Conversely, HK2 dissociation promotes mitochondrial injury and decreases tumor growth, which makes it an attractive target for the development of anticancer therapies." (PMID 29298880, 2018). "The subsequent overexpression of hK2 as a response to therapy creates a feed-forward loop that promotes binding more [225Ac]hu11B6 as shown in the upward trajectory of tumor accumulation of drug despite decreasing volume." (PMID 29691406, 2018). "HK2 promotes tumor survival and resilience of cell death, where its mitochondrial dissociation was found to trigger apoptosis in cancer cells." (PMID 29298880, 2018). "Our initial goal was to identify a tumor population likely to be highly sensitive to HK2 inhibition or silencing, to optimize evaluation of targeting HK2 as a therapeutic modality." (PMID 29988332, 2018). "The complex I inhibitor metformin inhibited the increase in OXPHO, and the combination of HK2 ablation and metformin were synergistic in increasing cell death and in inhibiting tumor growth in vivo." (PMID 29386513, 2018). "Accordingly, HK2 silencing and metformin treatment had a synergistic effect on tumor growth in vivo." (PMID 29386513, 2018). "The deletion of HK2 in the prostates of Pbsn-Cre4;Ptenf/f mice inhibited tumor growth and markedly extended their survival." (PMID 29687779, 2018). "Previous reports have shown that HK2 is an important regulator of tumor growth and the Warburg effect." (PMID 29696133, 2018). "Hexokinase 2 (HK2) is the predominant isozyme that is overexpressed in tumours and contributes to aerobic glycolysis." (PMID 29156804, 2017). "The HK2-VDAC interaction prevents tumor cells from undergoing apoptosis by inhibiting the release of cytochrome c from mitochondria through the VDAC36." (PMID 28186160, 2017). "Warburg effect is one of the most fundamental metabolic alterations during tumor development and progression, of which the over-expressed hexokinase 2 (HK2) plays a crucial role in glycolytic pathway." (PMID 28427443, 2017). "The binding of HK2 to VDAC is the key event in antiapoptosis in tumor cells, which helps to decrease the formation of permeability transition pores (PTPs) in OMM and prevent subsequent release of pro-apoptotic proteins such as cytochrome c." (PMID 28415659, 2017). "Hexokinase 2 (HK2) was the crucial enzyme controlling the first step of glycolysis, and systemic deletion of HK2 can impair the tumor progression in mouse models." (PMID 29371926, 2017). "At the end of treatment an average reduction in tumor volume of 57.5% was observed with HK2 knockdown (P=0.020)." (PMID 28915575, 2017). "We focused on the functional significance and regulatory mechanisms of the miR-125a/HK2 axis in the regulation of the Warburg effect and tumor growth in vitro and in vivo." (PMID 28596599, 2017). "Along with the increase of HK-2, altered glucose metabolism often conferred cancer cells resistance to chemotherapy, it was evidenced that the sensitivity of tumor cells to chemotherapy were substantially enhanced via glycolysis inhibition by targeting HK-2." (PMID 28320429, 2017).
tumor (continued). "Briefly, the present study suggests that glycolysis is involved in HOTAIR/miR-125- and miR-143/HK2-mediated tumour activation." (PMID 29156804, 2017). "In vivo, our data demonstrated that interleukin-22 significantly promoted tumor growth along with elevated expression of c-Myc and hexokinase-2 in mice." (PMID 28445985, 2017). "Reportedly, HK2 is overexpressed in tumours and it is documented as a metabolic target for cancer therapy." (PMID 29156804, 2017). "This indicates the importance of maximal glycolysis, and thus HK2, in tumor survival and progression." (PMID 29220380, 2017). "As we expected, rescue of HK2 in miR-143 overexpressing cells led to marked enhancement of the cellular proliferation, invasion and tumor glucose metabolism." (PMID 28174335, 2017). "HK2 is the enzyme controlling the first step of glycolysis, and systemic deletion of HK2 can impair the tumor progression in mouse models." (PMID 28427443, 2017). "HK2 plays a pivotal role in tumor initiation and maintenance, which provides a new target for cancer therapy." (PMID 28427443, 2017). "HK2 stimulates aerobic glycolysis which provides energy and the necessary building blocks for tumor cell growth." (PMID 29290953, 2017). "Stable knockdown of HK2 decreased primary tumor growth in cell line xenografts and decreased incidence of lung metastasis after tail vein injection." (PMID 28915575, 2017). "Strikingly, clinical retrospective analysis disclosed that high expression of HK2 in tumor tissue indicated poor prognosis." (PMID 28427230, 2017). "Taken together, when tumour cells are rich for glucose, both HK1 and HK2 are essential for c-Src stimulated maximum glucose flux required for rapidly proliferating tumour cells." (PMID 28054552, 2017). "For example, miR-122 and its host gene regulate cholesterol and lipid metabolism in liver; miR-143 and its target gene, HK2, regulates aerobic glycolysis in tumor cells." (PMID 29137232, 2017). "Our findings here revealed that targeting HK2 also contributed to the tumor suppressive activity of miR-125a." (PMID 29043013, 2017). "Previous studies reported that tumor cells with high HK-2 expression often displayed high glycolytic phenomenon, we also investigated the effect of chrysin on tumor glycolysis." (PMID 28320429, 2017). "The HK2 silenced U87 and U251 cell lines were assessed for their proliferation, migration and invasive potential in vitro, while the tumor forming potential of U87 cells was evaluated in vivo." (PMID 29220380, 2017). "Substitution of cellular HK1 or HK2 with their corresponding mutants significantly diminishes c-Src stimulated glucose uptake, retarded proliferation and dampened xenograft tumour growth in nude mice." (PMID 28054552, 2017). "This increase in HK2 expression was unrelated to age and gender of the assessed patients, but was positively correlated with tumor stage." (PMID 29220380, 2017). "But, the exact mechanism involved in HK2-mediated tumor progression, however, remains largely unexplored." (PMID 29220380, 2017). "The growth of tumours derived from CAL27 cells infected with the HK2 shRNA was significantly suppressed compared with that of tumours derived from CAL27 cells infected with control shRNA." (PMID 27926482, 2017). "Herein, high intensity of HK2 facilitates tumor progression through different pathways, which is contributed to poor prognosis in solid tumors of digestive system." (PMID 28415659, 2017). "The results revealed that HK2 and LCN2 are associated with tumor progression, especially in LUSC tissue." (PMID 29285270, 2017). "With the suppression of glycolysis by reducing HK-2 in tumor tissue, energy supply to sustain tumor growth was blocked, and the proliferative capability of tumor cell was weakened." (PMID 28320429, 2017).
tumor (continued). "Immunohistochemistry analysis of chrysin-treated tumor tissue demonstrated the expression of HK-2 in tumor tissue was substantially decreased after chrysin treatment, which confirmed the effect of chrysin on HK-2 in vivo." (PMID 28320429, 2017). "By contrary, HK2 is observed to be high expressed in several types of tumor cell, indicating that it plays a critical role in tumor initiation and development." (PMID 28415659, 2017). "As a consequence of its tumor-promoting potential and elevated expression in many tumors, HK2 is discussed to serve as a novel target for cancer therapy." (PMID 29290953, 2017). "Another key driver of tumor metabolism is Hexokinase 2 (HK2), an enzyme that converts glucose to glucose-6-phosphate." (PMID 27588472, 2016). "Consistent with limited effects of adipocyte ATGL inhibition on lipid uptake by the tumor cells, only modest reduction in mRNA levels of ENO2 and HK2 was revealed indicating limited impact on glycolytic phenotype in the tumor cells." (PMID 27588494, 2016). "STRING analysis confirmed protein-protein-interactions of regulated genes and Western immunoblotting of fatty acid synthase, serine hydroxyl-methyltransferase 1, arginine 1 and hexokinase 2 showed tumor specific induction." (PMID 27602772, 2016). "The hexokinase 2 (HK2) glycolytic enzyme is highly expressed in tumours, and miR-143, which targets HK2, has been found downregulated in cancer cells." (PMID 27213336, 2016). "HK2 is rarely expressed in normal tissues, except skeletal and cardiac muscle and adipose tissues; however, it is frequently upregulated in tumor cells, leading to a phenomenon known as the Warburg Effect." (PMID 27260001, 2016). "In has been shown that in tumor cells cytosolic HK1 and HK2 were tightly associated to the voltage-dependent anion channel (VDAC) in the mitochondrial membrane." (PMID 28105937, 2016). "The Ki67 IHC staining in xenograft tumor also showed that up-regulation of HK2 significantly increased in Kras-knockdown KP2 cells (P = 0.0066)." (PMID 26884725, 2016). "HK2 protein and mRNA expression in tumor tissues were detected in 18 and three studies, respectively." (PMID 27824926, 2016). "The overexpression of HK2 provides tumor cells with a growth advantage due to increased glycolytic activity, prevents from apoptosis, and increases their possibility for metastasis." (PMID 28105937, 2016). "Both FDGhi and FDOPAlo phenotypes correlated with higher HK2 expression, which is required for oncogenic transformation in vitro and tumor initiation in vivo and is enhanced by MYCN and HIF-1α." (PMID 26959748, 2016). "We demonstrate that the survival benefit provided by inhibition of HK2 is tumor growth stage-dependent." (PMID 27588472, 2016). "This is also the evidence that HK1 and HK2 are responsible for the accelerated glucose flux in tumor cells." (PMID 28105937, 2016). "2-DG inhibits cell growth and tumor proliferation in vitro and in vivo by inducing tumor cell apoptosis and autophagy through targeting HK2." (PMID 26884725, 2016). "Meanwhile, HK is involved in the initiation and progression of tumor; in particular, HK2 is a critical component integrating cell viability and energy production pathways." (PMID 27824926, 2016). "Hypoxia-inducible factor-1α (HIF-1α) induces aggressive tumor phenotypes by regulating more than 60 target genes, including HK2." (PMID 27260001, 2016). "Comparatively, HK2 KD tumors demonstrated distinctive histological regions, including a necrotic center surrounded by proliferative tumor cells in the periphery, and a border zone containing predominantly neutrophils." (PMID 27588472, 2016). "It has been observed that the tumor cells adapted metabolically primarily by increasing the expression of HK2." (PMID 28105937, 2016). "Mice with HK2 KD tumors showed smaller tumors compared to control, confirming a reduction in tumor size, using both DCE-MR images and T1-weighted with contrast (T1w) MR images." (PMID 27588472, 2016).